EZH2 (enhancer of zeste 2 polycomb repressive complex 2 subunit)
Diseases named in the same sentence as EZH2 in open-access papers (continued):
Sharing a sentence is not in itself a finding about the gene and the disease.
bladder cancer (continued). "For example, in an animal model of bladder cancer, treatment with EZH2 inhibitor enhanced the infiltration of NK cells into the tumor microenvironment, through upregulation of CCL3." (PMID 40551137, 2025). "ARID1A‐deficient bladder cancer cells are sensitive to PI3K inhibitors, and combined use with EZH2 inhibitors can achieve synergistic anti‐tumour effects." (PMID 39779467, 2025). "Recent studies from bladder cancer and rhabdomyosarcoma demonstrated the efficacy of combining certain EZH2 inhibitors with retinoid compounds." (PMID 40101298, 2025). "In a carcinogen-induced bladder cancer model, inhibition of EZH2 resulted in significantly reduced tumor progression only when the adaptive immune system was intact–in mice lacking T-cells, EZH2 inhibitors had little effect." (PMID 40918525, 2025). "Thirdly, further large-scale population-based prospective studies are needed to confirm the efficiency of serum EZH2 as a biomarker for bladder cancer screening and monitoring." (PMID 38476362, 2024). "We also used the Cox regression model and log-rank test to investigate the correlation between EZH2 levels and clinicopathological characteristics, and survival rates of bladder cancer patients." (PMID 38476362, 2024). "EZH2 can promote the proliferation and migration of bladder cancer cells by activating JAK2/STAT3 signalling pathway." (PMID 38506082, 2024). "Downregulation of SIRT7 orchestrates EMT and promotes metastasis in bladder cancer cells because of the inhibition of E-cadherin mediated by enhancer of zeste homolog 2 (EZH2) methyltransferase." (PMID 37676263, 2024). "In the present study, we examined the expression patterns of EZH2 in both bladder cancer tissues and serum samples of patients." (PMID 38476362, 2024). "Correlations between EZH2 levels and clinicopathological characteristics of bladder cancer patients for continuous variables." (PMID 38476362, 2024). "High EZH2 levels correlated with poor overall survival rates and progression-free survival rates of bladder cancer patients." (PMID 38476362, 2024). "Given the efficiency, convenience, and cost-effectiveness of serum tumor markers in cancer screening, serum EZH2 holds the potential as a biomarker for bladder cancer screening." (PMID 38476362, 2024). "Serum EZH2 levels were elevated in bladder cancer patients, and patients with higher serum EZH2 levels exhibited a poorer prognosis." (PMID 38476362, 2024). "This study also demonstrated that bladder cancer patients with higher serum EZH2 levels had lower overall survival rate and progression-free survival rate than patients with lower serum EZH2 levels." (PMID 38476362, 2024). "Accordingly, the knockdown of TUG1 in bladder cancer cells lowers EZH2 expression, thereby reducing miR-194-5p methylation and inducing its expression." (PMID 38256203, 2024). "Our preliminary study found that serum EZH2 has the potential to be a biomarker for bladder cancer diagnosis and prognosis." (PMID 38476362, 2024). "In another related study, the authors also reported a high sensitivity of bladder cancer cells to EZH2 inhibition alone, or in combination cisplatin treatment in the presence of KMD6A and SWI/SNF mutations." (PMID 39118085, 2024). "Correlations between EZH2 levels and clinicopathological characteristics of bladder cancer patients for categorical variables." (PMID 38476362, 2024). "On the other hand, the crucial regulatory involvement of SIRT7 and EZH2 in bladder cancer development is well known." (PMID 39719443, 2024). "The primary objective of this study was to examine the levels of serum EZH2 in patients diagnosed with bladder cancer, and subsequently evaluate its potential as a biomarker for both the diagnosis and prognosis of bladder cancer." (PMID 38476362, 2024). "Serum EZH2 levels were significantly higher in bladder cancer patients when compared to those in healthy persons." (PMID 38476362, 2024).
bladder cancer (continued). "We further used Kaplan–Meier analysis to assess the survival difference between bladder cancer patients with high serum EZH2 levels and low serum EZH2 levels based on the median EZH2 levels." (PMID 38476362, 2024). "Previous studies indicate that EZH2 is overexpressed in bladder cancer tissues, playing an important role in tumor metastasis and recurrence." (PMID 38476362, 2024). "In this study, we found that EZH2 expression levels were significantly elevated in bladder cancer tumor tissues and serum samples of bladder cancer patients." (PMID 38476362, 2024). "At a cutoff value of 8.23 ng/mL, EZH2 was able to differentiate bladder cancer patients from healthy persons, with an AUC of 0.87, a sensitivity of 81.31%, and a specificity of 78.42%." (PMID 38476362, 2024). "UNC1999 is another EZH2 inhibitor that is observed to have an anti-tumorigenic effect on human bladder cancer cells." (PMID 36980741, 2023). "There is also an inverse correlation between EZH2 levels and immune-related transcripts in bladder cancer." (PMID 37565053, 2023). "Several studies have reported that bladder cancers showing mutations in KDM6A, the gene coding for LSD-6A, are especially susceptible to EZH2 inhibition." (PMID 36980741, 2023). "In vivo and in vitro EZH2 inhibition in bladder cancer significantly upregulates CIITA levels and tsMHC-II and the efficacy of therapy in vivo is wholly dependent on adaptive immunity." (PMID 37565053, 2023). "Inhibition of EZH2 in ARID1Adef bladder cancer cells results in upregulation of PIK3IP1, an endogenous inhibitor of PI3K signaling." (PMID 35852858, 2022). "Overexpression of EZH2 is reported in many malignancies, such as breast, ovarian, prostate, and bladder cancer." (PMID 36428492, 2022). "In conclusion, ARID1A-deficient bladder cancers are dependent on PI3K signaling, which can be pharmacologically targeted with EZH2 and/or PI3K inhibitors." (PMID 35852858, 2022). "Authors have shown that H19 overexpression increased the migratory properties of bladder cancer cells by interaction with EZH2 which leads to activation of Wnt/β-catenin signaling and therefore led to EMT induction." (PMID 36685879, 2022). "For the events upstream of EZH2 activation in bladder cancer models, it was shown that lncRNA TUG1 promoted cisplatin resistance via regulation of the CCND2 through EZH2-associated silencing of miR-194-5p." (PMID 36230683, 2022). "For example, the LncRNA SPRY4-IT1 can sponge miR-101-3p, and therefore up-regulate EZH2 expression, which promotes proliferation and metastasis of bladder cancer cells." (PMID 35179516, 2022). "More importantly, it has been detected in a prior study that FGF2 is capable of upregulating EZH2 in bladder cancer cells, which was partially consistent with our result." (PMID 35177106, 2022). "What’s more, in bladder cancer, H19 has been found to interact with polycomb repressive complex 2 (PRC2) by associating with enhancer of zeste homolog 2 (EZH2), which leads to the silencing of the E-cadherin gene." (PMID 36246634, 2022). "The authors showed that EZH2 knockdown increased the sensitivity of the T24 bladder cancer cells to gemcitabine and cisplatin, while EZH2 overexpression decreased their sensitivity." (PMID 36230683, 2022). "EZH2 inhibits the E-cadherin promoter activity through methylating of H3K27me3 and promotes bladder cancer cell invasion and metastasis." (PMID 36497343, 2022). "In aggressive bladder cancers, EZH2 expression is high and promotes proliferation of bladder cancer cells." (PMID 35852858, 2022). "Prior studies have shown a high fraction of bladder cancers express the methyltransferase EZH2, a key component of the PRC2 complex, a protein complex with a central role in pluripotency and embryogenesis." (PMID 36192513, 2022). "Intriguingly, another work elucidated that FGF2 can increase enhancer of zeste homolog 2 (EZH2) expression by activating KDM2B in bladder cancer cells." (PMID 35177106, 2022).
bladder cancer (continued). "For various bladder cancer cell lines with ARID1A-truncating mutations or shRNA-mediated depletion, our experiments revealed that EZH2 inhibition is synthetically lethal for bladder cancer cells with ARID1A deficiency." (PMID 35852858, 2022). "EZH2 activity has been shown to be upregulated in a variety of malignancies, such as breast, prostate, and bladder cancers, preferentially complicated by osteolytic bone metastasis, in which augmented osteoclast differentiation plays a crucial role." (PMID 34571873, 2021). "LncRNA SPRY4-IT1 enhances the growth along with the metastasis of bladder cancer cells though sponging miR-101-3p to increase EZH2 expression." (PMID 33859998, 2021). "lncRNA H19 has been reported to accelerate bladder cancer metastasis by recruiting EZH2 and repressing the expression of E-cadherin." (PMID 34401209, 2021). "More specifically, GAS5 has the potential to inhibit EZH2 transcription by directly interacting with E2F transcription factor 4 (E2F4) and recruiting E2F4 to the promoter of EZH2 in bladder cancer cells." (PMID 34781960, 2021). "A previous study reported downregulation of AOX1 in advanced bladder cancer due to methylation modification by EZH2." (PMID 34290740, 2021). "AWPPH/EZH2 attenuates the apoptosis of bladder cancer by silencing SMAD4 by way of histone methylation on H3K27me3." (PMID 33050646, 2020). "We believed that there was a presence of lnc00518/miRNA-101/EZH2 axis involving in the pathogenesis of bladder cancer." (PMID 32047553, 2020). "Lnc00518 promotes the proliferative, invasive and migratory potentials of bladder cancer by upregulating EZH2 via competitively binding to miRNA-101." (PMID 32047553, 2020). "The study using KDM6A-knockout bladder cancer cells and patient-derived xenograft model suggested that EZH2 (enhancer of zeste homolog 2, H3K27 methylase) inhibition is a potential therapeutic target for bladder cancer with the mutations." (PMID 32842545, 2020). "EZH2 overexpression correlated with poor prognosis in tumors including prostate, breast, and bladder cancer." (PMID 32924329, 2020). "Lnc00518 promotes the proliferative, invasive and migratory potentials of bladder cancer by competitively binding to miR-101 to upregulate EZH2 expression." (PMID 32047553, 2020). "Most notably, upregulated lncRNA GAS5 has been demonstrated to inhibit the transcription of EZH2 via recruitment of E2F4 to EZH2 promoter and induced cell apoptosis of bladder cancer." (PMID 32308561, 2020). "Rescue experiments were conducted to elucidate the role of lnc00518/miRNA-101/EZH2 axis in bladder cancer." (PMID 32047553, 2020). "Some authors argue that the downregulated miR-143 is regulated by the oncoprotein EZH2, frequently overexpressed in bladder cancer, representing an important therapeutic target not only a biomarker." (PMID 31665050, 2019). "Another study shows that chemo-resistant tumors from bladder cancer patients maintain or overexpress EZH2 protein levels after chemotherapy compared to patients who are chemo-sensitive." (PMID 30692641, 2019). "In particular, HOTAIR was shown to mediate recurrence and progression in bladder cancer via the histone methyltransferase EZH2." (PMID 31195674, 2019). "In conclusion, our results suggest that bladder cancer cells and xenografts with KDM6A and SWI/SNF family member mutations can benefit from EZH2 inhibition that increases NK cell activity leading to reduction in cells with pluripotency potential." (PMID 30692641, 2019). "In our studies, EZH2 inhibition in HT1376 and T24 bladder cancer cells with KDM6A and/or SWI/SNF family member mutations increased levels of transcripts associated with NK cell activity." (PMID 30692641, 2019). "Our results indicate that EZH2 inhibition alone and in combination with cisplatin boosts NK cell response to drive tumor differentiation and death in bladder cancer cells and xenografts." (PMID 30692641, 2019).
bladder cancer (continued). "Our results reveal a novel sensitivity of muscle-invasive bladder cancer cells with KMD6A and SWI/SNF mutations to EZH2 inhibition alone and in combination with cisplatin." (PMID 30692641, 2019). "To summarize, cisplatin treatment, downregulation of EZH2 protein by siEZH2 and pharmacological inhibition of EZH2 activity alter the expression of pluripotency markers in a subset of tested bladder cancer cells." (PMID 30692641, 2019). "Taken together, our findings demonstrated a tumor-suppressor role of GAS5 by inhibiting EZH2 on transcriptional level, and additionally provided a novel therapeutic strategy for treating human bladder cancer." (PMID 29445179, 2018). "The Rb-E2F signaling pathway up-regulates EZH2 expression by binding to the promoter of EZH2 in bladder cancer and small cell lung cancer." (PMID 30120321, 2018). "In contrast to current data in bladder cancer, we even observed an increase in the colony forming ability of EZH2-depleted J82 cells that was more pronounced in the ARID1A-deficient background." (PMID 30138427, 2018). "This phenomenon indicated that the higher expression of EZH2 was dependent on aggressive pathological hallmarks including grade and stage in human bladder cancer." (PMID 30542123, 2018). "In bladder cancer, H19 was shown to direct EZH2 to the promoter region of Nkd1, thus inducing the trimethylation of H3K27 and the consequent repression of transcriptional activity." (PMID 29643989, 2018). "EZH2 was found to be regulated by E2F1, which was previously linked to aggressiveness and prognosis of bladder cancer." (PMID 30072631, 2018). "In summary, to our knowledge, this is the first study to date that has evaluated EZH2 expression in bladder cancer in a Chinese population." (PMID 30542123, 2018). "We demonstrated that EZH2 is a potential target of bladder cancer treatment in basic medical research and identified its clinical implications in patients with bladder cancer." (PMID 28968986, 2017). "The cancer genome atlas (TCGA) data showing a correlation between KDM2B and EZH2 expression and Oncomine data, showing a correlation between KDM2B and tumor progression, strongly support the role of the FGF-2/KDM2B/miR-101/EZH2 pathway in bladder cancer." (PMID 28515962, 2017). "Further, BDR4 regulates EZH2 transcription by upregulating c-Myc, thereby suggesting a novel therapeutic target in bladder cancer." (PMID 28410242, 2017). "The T24 bladder cancer cells with EZH2 knockdown, EZH2 overexpression, and blank vectors, as well as wild-type cancer cells were cultured with WF, and the survival rates were assessed in vitro using the CD-DST after treatment with the anticancer drug DDP." (PMID 28968986, 2017). "Here we show, using clinical samples and bladder cancer cell lines, a functional interaction between EZH2- and PIK3CA-dependent signaling pathways." (PMID 28060766, 2017). "The present study investigated the effect of zeste homolog 2 (EZH2) and wound fluid (WF) on chemotherapy sensitivities of T24 bladder cancer cells by using a collagen gel droplet embedded culture-drug sensitivity test (CD-DST)." (PMID 28968986, 2017). "T24 bladder cancer cells with different EZH2 expression levels were co-cultured with postoperative WF from patients with bladder cancer." (PMID 28968986, 2017). "LncRNA SPRY4-IT1 directly interacts with and inhibits miR-101-3p expression, leading to EZH2 upregulation and enhanced proliferation and metastasis in bladder cancer T24T cells." (PMID 28947955, 2017). "First, changes in EZH2 expression affected the sensitivities of bladder cancer cells to chemotherapy drugs." (PMID 28968986, 2017). "EZH2 silencing also resulted in significantly decreased cell proliferation and reduced G1 to S phase transition in bladder cancer cells." (PMID 28122346, 2017).
bladder cancer (continued). "The T24 bladder cancer cells with EZH2 knockdown, EZH2 overexpression, and blank vectors, as well as the wild-type cancer cells were cultured with WF, and the survival rates were assessed in vitro using the CD-DST after treatment with gemcitabine." (PMID 28968986, 2017). "Our results were similar to those of previous studies, but we focused on EZH2, which is a novel and interesting angle from which to explore chemotherapy drug resistance in bladder cancer." (PMID 28968986, 2017). "Increased expression and protein levels of EZH2 has been reported in highly advanced bladder cancer specimens." (PMID 28122346, 2017). "We knocked down and upregulated the expression of EZH2 in parallel groups of bladder cancer cells to compare its biological effects on T24 bladder cancer cells from two opposing perspectives." (PMID 28968986, 2017). "One possible mechanism would be a decrease of C-Myc recruitment to EZH2 and consequently reduced EZH2 expression, as shown in bladder cancer." (PMID 28672805, 2017). "Nuclear H19 binds EZH2, a key component of Polycomb repressive complex 2, and inhibits the transcription of a selective group of genes, thereby promoting bladder cancer metastasis." (PMID 27063004, 2016). "As a matter of fact, another group previously demonstrated the H19 activated Wnt/β-catenin pathway by interacting with the RNA binding protein Enhancer of zeste homolog 2 (EZH2), leading to enhanced bladder cancer metastasis." (PMID 26853553, 2016). "Overexpression of EZH2 has been shown to have an important role in various malignancies, including breast, prostate, gastric, hepatic, and bladder carcinoma." (PMID 27793210, 2016). "The analysis of HOTAIR and EZH2 expression in nine different non-invasive bladder cancer cell lines also showed that those cells showing high EZH2 protein levels also displayed high HOTAIR expression, thus reinforcing their co-regulation." (PMID 26457124, 2015). "In order to test the role of EZH2 in bladder cancer cells, we knocked down EZH2 by small interfering RNA and found its depletion reduced cell proliferation by 33.9% and 27.9%, 72 h after siRNA transfection." (PMID 26484567, 2015). "Consistently, Guo and co-workers reported that miR-144 suppression induces an increase in bladder cancer cell proliferation through targeting EZH2 and regulating Wnt signaling." (PMID 25912304, 2015). "Our data suggest a promising therapeutic option to develop drugs targeting EZH2/miR-143 axis, such as honokiol, for bladder cancer treatment." (PMID 26484567, 2015). "The observed HOTAIR regulation by EZH2 and the possibility of modulating EZH2 activity with specific inhibitors open new possible paths to be explored in bladder cancer therapy." (PMID 26457124, 2015). "In agreement, knockdown of EZH2 in RT112 bladder cancer cells produced the overall upregulation of all miR-200 members without significant changes in BMI1 protein." (PMID 26517683, 2015). "The availability of genetically engineered mice recapitulating the EZH2 oncogenic activity in bladder cancer warrant preclinical test of this possibility." (PMID 26517683, 2015). "EZH2, a major histone methyltransferase in PRC2 complex, has been implicated in various cancer types, including prostate, lung and bladder cancer." (PMID 26484567, 2015). "Collectively, these results indicated that EZH2 activity negatively controls the miR200 family expression in bladder cancer." (PMID 26517683, 2015). "For example, Wang and colleagues have demonstrated that miR-101 sensitizes human bladder cancer cells to gambogic acid-induced apoptosis by inhibiting EZH2 expression." (PMID 26036638, 2015). "Using overexpression, knockdown, and pharmacological approaches in bladder cancer cell lines, we also observed that EZH2 regulates HOTAIR expression." (PMID 26457124, 2015). "Another miRNA gene, miR-144, was downregulated and had reported increased bladder cancer cell proliferation by targeting EZH2 and regulating Wnt signaling." (PMID 24982669, 2014).